PDCD1 (programmed cell death 1)
Diseases named in the same sentence as PDCD1 in open-access papers (continued):
Sharing a sentence is not in itself a finding about the gene and the disease.
cancer (continued). "Use of anti-programmed cell death-1 (anti-PD-1) has been successful in treating many types of cancers." (PMID 30012209, 2018). "For example, the co-inhibitory receptor programmed cell death 1 (PD-1) plays a key role in cancer immune, especially in the immune escape phase." (PMID 29435162, 2018). "Programmed cell death ligand 1 (PD-L1) is a potential predictive biomarker of the response to anti-PD-L1/anti- programmed cell death 1 (PD-1) therapy in multiple cancers, including triple negative breast cancer(TNBC)." (PMID 29291717, 2018). "Programmed cell death 1 (PD-1) inhibitors block a signal preventing activated T cells from attacking cancer cells." (PMID 30153300, 2018). "Based on efficacy results from pivotal randomized clinical trials, PD-1 (programmed cell death 1) inhibitors, such as nivolumab and pembrolizumab, have been approved to treat various cancers." (PMID 30646078, 2018). "Nivolumab, an anti-programmed cell death-1 (PD-1) monoclonal antibody used as an immune checkpoint inhibitor, is commonly employed for its anti-tumor effects against various types of malignant tumors." (PMID 29378571, 2018). "Programmed cell death-1 (PD-1)/programmed death ligand-1 (PD-L1) blockade therapy has improved clinical outcomes in many types of malignant tumors." (PMID 29593736, 2018). "While absolute PDCD1 expression on average varies considerably between cancer types (left), normalizing the expression within each cancer type would serve to subtract out such differences (right)." (PMID 28775315, 2017). "The gene signature associated with this phenotype, additionally including immune regulatory genes IDO1, FOXP3, PDCD1, CTLA4, and CD274/PD-L1, has been associated with an improved prognosis in multiple cancer types." (PMID 29064420, 2017). "Recently, FDA approves the first cancer treatment for any solid tumor with a specific genetic feature, which works by targeting the programmed cell death-1 (PD-1)/PD-L1 immune checkpoint pathway." (PMID 31725860, 2017). "Recent clinical studies targeting co-inhibitory and co-stimulatory immune checkpoints such as cytotoxic T lymphocyte protein-4 (CTLA-4), programmed cell death 1 (PD-1) and its ligand (PD-L1) have demonstrated anti-tumour activity in several cancer types." (PMID 28122336, 2017). "Programmed cell death 1 (PD-1) and its ligands PD-L1/PD-L2 have been shown to mediate immune evasion in various cancers, but their prognostic implications in patients with primary central nervous system lymphoma (PCNSL) are poorly understood." (PMID 29152083, 2017). "The discovery of immune system checkpoint inhibition, like programmed cell death-1 (PD-1), has revolutionized the treatment of several types of cancers and is being actively explored in HGSOC." (PMID 29057791, 2017). "Many human cancers have been reported to have enhanced expression of the immune checkpoint molecule programmed death-ligand 1 (PD-L1), which binds to programmed cell death-1 (PD-1) expressed on immune cells." (PMID 28160557, 2017). "Programmed death ligand-1 (PD-L1) is expressed in various tumors, and antibodies targeting its receptor programmed cell death 1 (PD-1) are emerging cancer therapeutics." (PMID 28125702, 2017). "Major breakthroughs have been achieved in agents targeting immune checkpoint proteins, such as cytotoxic T lymphocyte antigen-4 (CTLA-4) and programmed cell death-1 (PD-1), in patients with various types of cancer." (PMID 28620797, 2017). "Recent successes in immune checkpoint blockade such as targeting CTLA-4 (cytotoxic T-lymphocyte antigen 4) and/or PD-1/PD-L (programmed cell death 1/PD-1 ligand) have fueled the treatment for cancers." (PMID 27121051, 2016). "Pembrolizumab is an FDA-approved therapeutic antibody that targets the programmed cell death-1 (PD-1) to block the immune checkpoint pathway for the treatment of various types of cancer." (PMID 27734966, 2016).
cancer (continued). "Anti-programmed cell death 1 (PD1) immunotherapies are among the most effective anti-cancer immunotherapies available; however, a large number of patients present with or develop resistance to them." (PMID 27782862, 2016). "Targeting the programmed cell death 1 (PD1)/programmed cell death-ligand 1 (PD-L1) pathway to improve the host immunity is a recent breakthrough in cancer immunotherapy and the clinical benefits have been reported in lung cancer." (PMID 28074102, 2016). "There is growing interest in the immunoregulatory receptor programmed cell death 1 (PD-1) and the corresponding B7 family of ligands as a pivotal mechanism of tumor immune tolerance and escape in cancer." (PMID 25871477, 2015). "ICIs block key interactions between cancer cells and checkpoint molecules such as cytotoxic T-lymphocyte-associated protein 4 (CTLA-4, e.g., ipilimumab), programmed cell death 1 (PD-1, e.g., nivolumab), and programmed cell death ligand 1 (PD-L1, e.g., atezolizumab)." (PMID 41304963, 2025). "This suggests that the upregulation of these genes, including PDCD1, TIGIT, and LGALS9, may be associated with a more favorable immune response and a lower risk of cancer progression or recurrence." (PMID 40747615, 2025). "Its function in the tumor microenvironment is to bind to the immune checkpoint protein programmed cell death-1 (PD-1), which is expressed on regulatory T cells, thereby inhibiting immunogenic effects by providing an “off” signal that allows cancer cells to evade the immune system." (PMID 40733128, 2025). "Studies have shown that the interaction of PDCD1 and its ligand leads to impaired T-cell function and immune evasion by cancer cells; therefore, targeting PDCD1 and its ligand with inhibitory drugs leads to the restoration of T-cell immune function and antitumor activity." (PMID 41249728, 2025). "This study highlights the context-dependent regulation of PDCD1 across cancer types." (PMID 40149458, 2025). "Six patients were allergic to chemotherapeutic agents (procarbazine, oxaliplatin, paclitaxel, and temozolomide), while the other two were allergic to anti-cancer immunotherapeutics targeting programmed cell death-1 (PD-1) or programmed cell death-ligand 1 (PD-L1)." (PMID 40869188, 2025). "The combination of targeted therapies with immunotherapy in the form of ICIs such as programmed cell death 1 (PD-1) has led to dramatic improvements in clinical outcomes for many cancers, but the results of monotherapy, namely, in PDAC, have been rather disappointing." (PMID 40226120, 2025). "Furthermore, we assessed the correlations between GBP4 and immune checkpoint genes, including TIGIT, CTLA4, CD274 and PDCD1, across cancers." (PMID 38347243, 2024). "The United States Food and Drug Administration has approved several immunotherapeutic agents for cancer treatment, such as cytotoxic T‐lymphocyte‐associated protein 4 (CTLA‐4) antibodies, programmed cell death 1 (PD‐1) inhibitors and programmed cell death 1 ligand 1 (PD‐L1) inhibitors." (PMID 39245957, 2024). "To this end, we explored the mutation rate of the Tex signature genes in pan-cancer, and we observed a 2–3% SNV mutation frequency of PDCD1, LAG3, TIGIT, HAVCR2, and LAYN mainly in UCEC and SKCM, with HAVCR2 and TIGIT having the highest mutation frequencies (24% and 23% of samples, respectively)." (PMID 39064019, 2024). "We retrospectively analyzed 418 patients treated with anti-programmed cell death 1(PD-1)/PD-1 ligand (PD-L1) inhibitors from January 2018 to May 2022 in our cancer center." (PMID 38267897, 2024). "In addition, we found that PDCD1 and CTLA4 were also associated with PTBP1 expression in these 3 cancer types." (PMID 38918441, 2024). "Of note, the in vivo levels of Pdcd1 (encoding PD-1) or Cd274 (encoding the PD-1 ligand PD-L1), both in vivo and in cultured cancer cells, were not altered by CDA depletion." (PMID 38844817, 2024).
cancer (continued). "Gene and protein networks indicative of T-cell dysfunctionality could be extracted from PDCD1/LAG3 omics signatures in human cancers." (PMID 39030301, 2024). "PDCD1, also known as PD-1, is a vital immune checkpoint gene for cancer immunotherapy, which interactions with PD-L1 negatively regulating adaptive immune response mainly by inhibiting the activity of effector T cells and enhancing the function of immunosuppressive Tregs." (PMID 39872538, 2024). "In addition, the occupational tumors showed the expression of programmed cell death ligand 1 in cancer cells and the presence of programmed cell death 1-positive T cells and CD-8 positive lymphocytes." (PMID 39444007, 2024). "The PDCD1-mediated pathway may be used by cancer cells to change the antitumor response and avoid the destruction by the immune system." (PMID 39897071, 2024). "Finally, we gathered the IC50 of a wide variety of drugs among different cancer cell lines through the GDSC and CTRP databases and tried to explore the possible associations with the corresponding CXCL13, HAVCR2, LAG3, TIGIT, PDCD1, and LAYN mRNA values." (PMID 39064019, 2024). "The programmed cell death 1 (PD-1) receptor is one of the crucial immune checkpoint molecules which dampens immune responses via engagements with its two ligands, PD-1 ligand 1 (PD-L1) and PD-L2 expressed by cancer cells." (PMID 39511147, 2024). "In BC, the expression of NKG2A is associated with a better response to anti-PD-L1 therapy in cancers with higher levels of CD8A, PDCD1, or PD-L1, suggesting that NKG2A could be a predictive biomarker." (PMID 39682686, 2024). "ICI therapy has proven to be a useful treatment for carcinoma, and we observed that the risk score was negatively correlated with the immune checkpoints CTLA4, ICOS, and PDCD1, suggesting that the sensitivity to immunotherapy may differ among subgroups." (PMID 38244579, 2024). "In a study, a meta-analysis was conducted to evaluate the efficacy of the anti-Claudin-18.2-targeted therapy, zolbetuximab, in comparison to other anti-programmed cell death-1/programmed cell death-ligand 1 (PD-1/PD-L1) inhibitors for treating gastric/gastroesophageal junction (G/GEJ) carcinoma." (PMID 39759684, 2024). "This dataset can be further probed by visualization of correlations with specific immunomodulators within a cancer indication of interest, as illustrated by the correlation of PDCD1 and CD27 expression in lung adenocarcinoma, as has been previously shown for breast cancer." (PMID 37457379, 2023). "Cancer immunotherapies targeting immune checkpoint pathways, such as programmed cell death-1 (PD-1)/programmed cell death ligand-1 (PD-L1) and cytotoxic T-lymphocyte-associated antigen-4 (CTLA-4), have achieved unprecedented therapeutic success in treating various types of cancer." (PMID 37614504, 2023). "PD-1 (Programmed cell death-1) is an important immunosuppressor molecule for cancer immunotherapy." (PMID 37416784, 2023). "Our findings revealed a positive correlation between the expression levels of LAG3 and IFNG (R = 0.76, p < 0.001), PRF1 (R = 0.75, p < 0.001), FASLG (R = 0.75, p < 0.001), GZMH (R = 0.74, p < 0.001), NKG7 (R = 0.74, p < 0.001), and PDCD1 (R = 0.73, P < 0 0.001) in pan-cancer tissues." (PMID 38115039, 2023). "CTLA4, LAG3, and PDCD1 are important targets for cancer ICI therapy." (PMID 38333724, 2023). "They express inhibitory receptors, such as PDCD1, TIM-3, TIGIT, LAG-3 and cytotoxic T-lymphocyte-associated protein 4 (CTLA4), which induce T-cell exhaustion and prevent T-cell activation; however, cancer cells utilize these receptors to evade T-cell attacks." (PMID 36979400, 2023). "Stem-cell-originating cancer cells co-localized with CD4+ T-cells expressing a high frequency of FOXP3+ cells, as well as upregulation of genes associated with exhaustion including Pdcd1, Ctla4, and Havcr2 (TIM3)." (PMID 37654482, 2023).
cancer (continued). "Interestingly, low-risk groups had higher PDCD1 and CTLA4 mRNA expression than high-risk groups, which was currently commonly used for immune checkpoints in cancers." (PMID 36930113, 2023). "Additionally, our results showed a significant correlation between PCSK9 expression with PDCD1 and CTLA4, which referred to T cell exhaustion and led to the loss of T cell function in patients with common chronic infections and cancer." (PMID 37860186, 2023). "Studies have shown that antibodies against CD274, CTLA-4, and PDCD1 (immune checkpoint molecules) could promote antitumor T cell activity and improve clinical outcomes in various cancers." (PMID 37851374, 2023). "ICIs such antibodies targeting programmed cell death 1 (PD-1), cytotoxic T lymphocyte-associated protein 4 (CTLA-4) and PD1 ligand 1 (PD-L1) have showed promising therapeutic effect and have been applied for many cancer types in the clinic." (PMID 36892953, 2023). "Programmed cell death-1 (PD-1) inhibitors as a type of ICIs are designed to boost T-cell activation and levels of proinflammatory cytokines along with concentrations of autoimmune antibodies against cancer by blocking PD-1 protein expression." (PMID 37404814, 2023). "Notably, one of these cancers acquired a genetic deletion of PDCD1 upon disease progression, whereas the others lost PDCD1 expression by still uncharacterized mechanisms." (PMID 37723306, 2023). "Cancer and stroma cells commonly induce the expression of programmed cell death ligand 1 (PD-L1) that binds to programmed cell death 1 (PD-1) on T cells and leads to their exhaustion, a known phenomenon during cancer development and in chronic viral infections." (PMID 36900377, 2023). "PDCD1 transcription has been demonstrated in over 30 cancers, including hematological malignancies." (PMID 35691988, 2023). "Currently, IMGT/mAb-DB includes 32 anti-PDCD1 mAbs for cancer immunotherapy." (PMID 37215135, 2023). "Interestingly, the findings suggested a correlation between HIF1AN in breast malignancy and PDCD1, LAG3, CTLA4, and GZMB of T cell exhaustion as well as chemokine ligand CCL2 of TAMs." (PMID 36816977, 2023). "In recent years, immune checkpoint inhibitors (ICIs), including anti-programmed cell death -1/programmed cell death ligand-1 (PD-1/PD-L1) and anti-cytotoxic T lymphocyte-associated antigen-4 (CTLA-4) agents, have revolutionized the management of cancer." (PMID 38187399, 2023). "At present, programmed cell death 1/programmed cell death ligand 1 (PD1/PDL1) and cytotoxic T lymphocyte-associated protein 4 (CTLA4) are the most well-studied signals and have shown impressive therapeutic benefits in different cancers." (PMID 35574031, 2022). "Conversely, in cancer cells, Pdcd1 overexpression increased both basal and DOX-induced apoptosis." (PMID 35190965, 2022). "Recently, cancer immunotherapy using immune‐checkpoint blockade (ICB) that targets programmed cell death 1 (PD‐1), programmed cell death‐ligand 1 (PD‐L1), programmed cell death‐ligand 2 (PD‐L2) and cytotoxic T‐lymphocyte‐associated protein 4 (CTLA‐4) provides significant clinical benefits in cancer." (PMID 34894053, 2022). "Moreover, hrHPV oncoproteins (E6/E7) stimulate the programmed cell death-1/programmed cell death-ligand 1 (PD-1/PD-L1) axis, thus leading to increased cancer progression." (PMID 36230832, 2022). "Fortunately, recent clinical trials of cancer immunotherapy have shown substantial survival benefits of antibodies against either programmed cell death-ligand 1 (PD-L1) or programmed cell death-1 (PD-1) in some types of cancer, including platinum-resistant or refractory EOC." (PMID 35719980, 2022). "Immunotherapy targeting immunological checkpoints, such as programmed cell death 1 (PD-1), programmed cell death 1 ligand 1 (PD-L1), and cytotoxic T lymphocyte-associated antigen-4 (CTLA-4), has been used as a potential therapeutic strategy for cancers." (PMID 35148766, 2022).
cancer (continued). "Therefore, the role of Pdcd1 in regulating apoptosis in cancer cells is in contrast to that in H9c2 cardiomyocytes." (PMID 35190965, 2022). "Among cancer immunotherapies, immune checkpoint blockade (ICB) which targets cytotoxic T lymphocyte antigen 4 (CTLA-4) or the programmed cell death 1 (PD1)–programmed cell death ligand 1 (PD­L1) axis has been approved for the treatment of several different cancer types." (PMID 35874784, 2022). "In addition, it has a role as a biomarker for familial cancer risk assessment and cancer prognosis; MSI status was found to predict the response to immune checkpoint inhibitors such as the programmed cell death 1 (PD-1) inhibitor." (PMID 35741173, 2022). "In this context, targeting immune checkpoints by blocking programmed cell death 1 (PD‐1) and/or programmed cell death 1 ligand 1 (PD‐L1) is one of the most promising new cancer therapies and has shown to improve progression‐free survival for triple‐negative BC (TNBC) patients." (PMID 34392603, 2022). "In recent decades, one of the major breakthroughs in cancer immunotherapy has been the discovery of immune checkpoint molecules, such as cytotoxic T-lymphocyte-associated protein 4 (CTLA-4), programmed cell death-1 (PD-1) and its ligand [programmed death-ligand 1 (PD-L1)]." (PMID 36284271, 2022). "For PDCD1 and TNFSF4, rs36084323 was associated with cancer risk." (PMID 36189300, 2022). "We also examined the role of Pdcd1 in DOX-induced apoptosis in cancer cells." (PMID 35190965, 2022). "In recent years, Immune checkpoint inhibitor (ICI) therapy has become one of the key systemic treatments for many malignant tumors, including Programmed Cell Death-1 (PD-1) and Programmed Cell Death ligand 1 (PD-L1) and Programmed Death ligand 2 (PD-L2) checkpoint ICIs." (PMID 34367944, 2021). "KO of ADAM17 and PDCD1 improved NK activity, cytokine production and cancer cell cytotoxicity." (PMID 34925314, 2021). "Although antibodies against the co-inhibitory receptors, cytotoxic T lymphocyte antigen 4 (CTLA-4) and programmed cell death 1 (PD-1), exhibit prominent efficacy in several cancer indications, only 20% of cancer patients respond to single-agent checkpoint inhibitors." (PMID 34708061, 2021). "Besides, several studies have investigated the prognostic role and clinical significance of programmed death‐1 (PDCD‐1) in treating cancer patients with PHI." (PMID 34672431, 2021). "In addition, the gene expression profiles of Prkag2 and Pdcd1 were analyzed in resident Tregs in patient cancer specimens using the available datasets (GSE89225) (r = − 0.621, p = 0.0034)." (PMID 34649584, 2021). "The breakthrough discovery of immune checkpoints such as cytotoxic T-lymphocyte antigen 4 (CTLA-4) and programmed cell death 1 (PD-1) had led to the development of immune checkpoint inhibitors (ICI) resulting in substantial changes in cancer treatment paradigms." (PMID 33890870, 2021). "CTLA4 and PDCD1 are immune checkpoint inhibitors that can be targeted for cancer immunotherapy." (PMID 34252931, 2021). "Most recently, the newly developed cancer fecal microbiota therapy in the clinical trial revealed that fecal microbiota transplant effectively promoted intra-tumoral immune activity and overcame resistance to anti-programmed cell death-1 immunotherapy." (PMID 34629100, 2021). "In parallel, the discovery of immune checkpoint molecules, such as programmed cell death 1 and cytotoxic T-lymphocyte antigen-4, has enabled a new strategy of cancer immunotherapy, and immune checkpoint inhibitors (ICIs) have dramatically improved the prognosis of various cancers." (PMID 34158541, 2021). "A better understanding of the biological mechanisms and functions of negative and positive co-stimulatory molecules has been shown to be essential for improving current and potentially new CTLA-4 or Programmed Cell Death 1 (PD-1) inhibitors for anti-cancer immunotherapies." (PMID 33809974, 2021).